NRG1 (neuregulin 1)
Diseases named in the same sentence as NRG1 in open-access papers (continued):
Sharing a sentence is not in itself a finding about the gene and the disease.
invasive carcinoma (1 paper, 2013). A carcinoma that is not confined to the epithelium, and has spread to the surrounding stroma. "For instance, studies of human breast tissues determined that NRG1 exon 1 (neuregulin 1) was partially methylated in 14 out of 17 (82.4%) of the invasive carcinomas samples tested, while it was unmethylated in 8 out of 10 of the normal breast tissues." (PMID 23762568, 2013).
ischemic cardiomyopathy (1 paper, 2025). Ischemic cardiomyopathy is a cardiomyopathy in which a weakness in the muscle of the heart due to inadequate oxygen delivery to the myocardium with coronary artery disease being the most common cause. "Clinical validation should determine whether pre-intervention NRG1 thresholds can identify patients most likely to benefit from moderate-intensity endurance protocols, particularly those with ischemic cardiomyopathy, where NRG1/ErbB signaling is essential for angiogenesis and fibrosis regression." (PMID 41000109, 2025).
left ventricular hypertrophy (1 paper, 2014). Enlargement of the LEFT VENTRICLE of the heart. "In multiple-phenotype analyses we find association of NRG1 with left ventricular hypertrophy phenotypes, fibrinogen and urea and pleiotropic relationships of F7 and F10 with Factor VII, Factor IX and cholesterol levels." (PMID 25329069, 2014). "New discoveries include gene-based association of NSF with triglyceride levels and several genes (ACSM3, ERI2, IL18RAP, IL23RAP and NRG1) with left ventricular hypertrophy phenotypes." (PMID 25329069, 2014).
malignant mesothelioma (1 paper, 2020). A malignant neoplasm of the pleura or peritoneum, arising from mesothelial cells. "In malignant mesothelioma cases, shed SDC-1 expression was significantly and positively correlated with HGF (p = 0.02; r = 0.3) and NRG1-b1 (p = 0.001; r = 0.4)." (PMID 32731396, 2020).
mesothelioma (1 paper, 2021). A usually malignant and aggressive neoplasm of the mesothelium which is often associated with exposure to asbestos. "Similarly, FGFR1 and its novel interactor NRG1 had elevated mRNA expression in H2722 mesothelioma cell lines and in MPM tissue, both contributing to increased cell growth under tumorigenic conditions." (PMID 33916178, 2021).
metastatic cancer (1 paper, 2022). A carcinoma which has spread from the original site of growth to another anatomic site. "Zenocutuzumab inhibited growth of NRG1 fusion-positive cancer models, also demonstrating efficacy in patients with chemotherapy-resistant NRG1 fusion-positive metastatic cancer." (PMID 36271429, 2022).
metastatic prostate carcinoma (1 paper, 2025). A carcinoma that arises from the prostate gland and has spread to other anatomic sites. "Collectively, these findings support that stroma-derived ASPN mediates paracrine activation of HER2/HER3 in metastatic prostate cancer while a subset of cancers may have additional autocrine or paracrine activation of HER2/HER3 signaling through NRG1." (PMID 40857406, 2025).
microcephaly (1 paper, 2023). A congenital or acquired developmental disorder in which the circumference of the head is smaller than normal for the person's age and sex. "More specifically, NRG1 has been shown to be expressed in the early stages of brain development, and it would be interesting to investigate the effect of its repression with respect to ZIKV-induced microcephaly." (PMID 37515107, 2023).
motor neuron degeneration (1 paper, 2019). "Mutations in the ALS19 gene lead to the reduced autophosphorylation capacity of the ErbB4 protein upon stimulation with NRG‐1, suggesting that the disruption of the NRG–ErbB4 pathway causes motor neuron degeneration." (PMID 31124187, 2019).
myocarditis (1 paper, 2019). Myocarditis is a condition that is characterized by inflammation of the heart muscle (myocardium). "Therefore, NRG-1 and its receptor ERBB4 may be of central importance to the recovery from acute and chronic CVB3 induced myocarditis." (PMID 31396490, 2019).
myopia (1 paper, 2023). "The increases in vitreous cavity length were significantly smaller in the NRG-1 antibody groups than in the myopia group, and these attenuation effects were dose-dependent." (PMID 37964886, 2023). "In the NRG-1 antibody groups, the relative expression of NRG-1 mRNA was significantly lower than that in the myopia group (p < 0.01)." (PMID 37964886, 2023). "The relative retinal NRG-1 mRNA expression was significantly higher in the myopia group than in the control group (p < 0.01)." (PMID 37964886, 2023). "Scleral and retinal thickness increased significantly in a dose dependent manner from the myopia group to the NRG-1 antibody groups." (PMID 37964886, 2023). "The relative NRG-1 mRNA expression in the retina was higher in the myopia group than in the control group." (PMID 37964886, 2023). "The relative expression of NRG-1, ERK1/2, and PI3K/AKT in the retina decreased in a dose-dependent manner from the myopia control group to the NRG-1 antibody groups and the normal control group." (PMID 37964886, 2023). "Comparing the NRG-1 antibody groups with the myopia group, both the sclera and retina were thicker at the posterior pole (p ≤ 0.001 and p = 0.10, respectively), and the sclera was also significantly thicker at the equator (p = 0.006), in the low-dose NRG-1 antibody group than in the myopia group." (PMID 37964886, 2023). "Correspondingly, in our study, the relative expression of the downstream signaling pathway members p-ERK1/2, p-PI3K, and p-AKT was higher in the myopia group than in the control group, while it was decreased in a dose-dependent manner in the NRG-1 antibody groups." (PMID 37964886, 2023). "Associations of NRG-1 with ocular axial elongation and axial myopia have not yet been described." (PMID 37964886, 2023). "When comparing the medium and high-dose NRG-1 antibody groups with the myopia group, the retina and sclera, measured at the posterior pole, equator and ora serrata, were significantly thicker in the medium and high-dose NRG-1 antibody groups than in the myopia group." (PMID 37964886, 2023).
nasopharyngeal carcinoma (1 paper, 2022). A carcinoma arising from the nasopharyngeal epithelium. "In addition, a large number of studies have been conducted on NRG1 fusion as a carcinogenic driving factor for many tumor types, including nasopharyngeal carcinoma." (PMID 35028969, 2022).
oral cavity tumors (1 paper, 2017). "Similarly, NRG1 overexpression was also observed in tongue and oral cavity tumors, relative to normal tongue and oral cavity tissue (unpublished observations)." (PMID 28723928, 2017).
oral squamous cell carcinoma (1 paper, 2019). "Lastly, the neuregulin 1 (NRG1) gene, a cell adhesion molecule, was previously reported to be upregulated in oral squamous cell carcinoma cells." (PMID 31892232, 2019).
osteosarcoma (1 paper, 2024). A usually aggressive malignant bone-forming mesenchymal neoplasm, predominantly affecting adolescents and young adults. "Somewhat surprisingly, OS-17 cells were insensitive to the growth factors PDGF-AA, PDGF-CC, FGF10, and NRG1, even at supraphysiological concentrations (100 ng/mL), which have been reported as having biological importance in osteosarcoma." (PMID 37676378, 2024).
ovarian failure (1 paper, 2021). "Similarly, a mouse model with granulosa cell-specific ablation of neuregulin 1 (Nrg1) showed signs of early ovarian failure where the estrous cycle stayed in a continuous, so-called, weak estrus." (PMID 34568325, 2021).
ovary (1 paper, 2024). "Our report of novel NRG1 gene rearrangements detected in serous carcinomas of the ovary, fallopian tube, and peritoneum indicates a small, but important prevalence of these fusions occurring within the female genital tract." (PMID 39575425, 2024).
pancreatitis (1 paper, 2022). Inflammation of the pancreas. "The autocrine loop of Nrg-1/2 with ErbB2/ErbB3 heterodimer elucidates the activation of downstream pathways and their crosstalk with one another as a key event in the conversion of normal stem cells into CSCs under inflammatory microenvironments such as pancreatitis." (PMID 35177646, 2022).
parasitemia (1 paper, 2014). "This indicates that NRG-1 therapy effectively reduces brain inflammation associated with ECM pathogenesis even in the presence of high parasitemia." (PMID 24433482, 2014).
paroxysmal AF (1 paper, 2018). "A previous study found a significant association between NRG-1 levels and the presence of paroxysmal AF." (PMID 30246788, 2018). "Our investigation demonstrated a potential mechanism of the NRG1/ErbB4 signaling system in a paroxysmal AF model." (PMID 30246788, 2018). "Therefore, pharmacological regulation of the NRG1/ErbB4 pathway is a potential treatment for patients in an early stage of AF (e.g., paroxysmal AF)." (PMID 30246788, 2018).
peritoneal carcinoma (1 paper, 2024). A peritoneum cancer that is located in the inside of the abdomen. "In one study of 21,858 tumor specimens, 0.4% of ovarian, fallopian tube, and primary peritoneal carcinomas were found to harbor NRG1 fusions." (PMID 39575425, 2024). "Of the 14,395 samples obtained from ovarian, fallopian tube, or primary peritoneal carcinomas that were tested by whole transcriptome sequencing, 26 were shown to harbor NRG1 fusions (incidence of 0.18%) between 2019 and 2023." (PMID 39575425, 2024).
pituitary adenomas (1 paper, 2020). "Druggable genes shared by all types of pituitary adenomas included NRG1, KCNA4, NCAM1, GRIA2 and GRM8." (PMID 33168897, 2020).
pleural mesothelioma (1 paper, 2021). A neoplasm that arises from the mesothelial cells of the pleura. "We collected the methylation profile of pleural mesothelioma, and found 8 novel interactors to be hypomethylated in pleural mesothelioma versus non-tumor pleural tissue, namely, ACVR1B, IL6, MGMT, NRG1, OAT, PHLDA2, PLAUR and TNC." (PMID 33916178, 2021).
primary immunodeficiency (1 paper, 2023). "Primary immunodeficiency (NES = -1.31, P = 0.15), neuroactive ligand-receptor interaction (NES = -1.38, p = 0.06), and drug metabolism other enzymes (NES = -1.53, P = 0.026) were enriched in the NRG1 low-expressed phenotype." (PMID 37061663, 2023).
prostate tumor (1 paper, 2022). "In addition, ABI treatment down-modulated NRG1, recently identified in prostate tumor microenvironment as directly involved in antiandrogen resistance." (PMID 36140255, 2022).
pulpitis (1 paper, 2025). Inflammation of the dental pulp. "Our findings revealed that NRG1, H3K9ac, and H3K27ac were up-regulated in pulpitis tissues, demonstrating a co-expression pattern among all three." (PMID 40580029, 2025). "NRG1 was up-regulated in human pulpitis samples, particularly within the odontoblast layer, whereas in the rat central pulp, rather than in the odontoblasts." (PMID 40580029, 2025). "However, NRG1 expression at the front of the lesion in pulpitis, particularly in the odontoblast layer, was significantly up-regulated (P < .01) compared to normal and carious teeth." (PMID 40580029, 2025).
radiation fibrosis (1 paper, 2013). "PTX alone or in combination with tocotrienols did not alter cardiac radiation fibrosis, left ventricular protein expression of the endothelial markers von Willebrand factor and neuregulin-1, or phosphorylation of the signal mediators Akt, Erk1/2, or PKCα." (PMID 23894340, 2013).
renal fibrosis (1 paper, 2021). A final common manifestation of a wide variety of chronic kidney diseases characterized by glomerulosclerosis and tubulointerstitial fibrosis. "Results revealed that lncRNA 74.1 and NRG1 were poorly expressed and miR-324-3p was highly expressed in renal fibrosis tissues and modeled cells." (PMID 34869303, 2021). "In other studies, HK-2 cells were stimulated with TGF-β1 to induce a cell model of renal fibrosis, followed by alteration on the expression of lncRNA 74.1, miR-324-3p, or NRG1, or by the addition of AKT activator SC79 in the HK-2 cells." (PMID 34869303, 2021). "Next, RT-qPCR and Western blot assays revealed that NRG1 expression was diminished upon aggravation of renal fibrosis." (PMID 34869303, 2021). "In this investigation, we set out to elucidate the potential interaction among long non-coding RNA ENST00000453774.1 (lncRNA 74.1), microRNA-324-3p (miR-324-3p), and NRG1, and to investigate their roles in the context of cellular autophagy and renal fibrosis." (PMID 34869303, 2021). "In addition, lncRNA 74.1 specifically bound to miR-324-3p and then stimulated NRG1 expression, which suppressed the renal fibrosis mediated by the PI3K/AKT signaling pathway." (PMID 34869303, 2021). "Findings concur in showing that lncRNA 74.1 could induce cellular autophagy and alleviate renal fibrosis by regulating the miR-324-3p-mediated NRG1/PI3K/AKT axis." (PMID 34869303, 2021). "Furthermore, we verified that lncRNA 74.1 promoted autophagy and inhibited renal fibrosis through NRG1." (PMID 34869303, 2021). "Furthermore, we tested whether miR-324-3p inhibited autophagy and promoted renal fibrosis by inhibiting NRG1 expression." (PMID 34869303, 2021). "Existing data suggests that NRG1 can inhibit the PI3K/AKT signaling pathway, which may suppress cellular autophagy and facilitate several fibrotic diseases including renal fibrosis." (PMID 34869303, 2021). "However, our study still presents with certain limitations regarding the relationship between EMT and renal fibrosis mediated by TGF-β signaling and how NRG1 might affects PI3K/AKT signaling pathway." (PMID 34869303, 2021).
serous carcinoma (1 paper, 2024). "This patient’s tumor represents a high grade serous carcinoma harboring a previously unreported NRG1 fusion; the gene is spliced with MYH10 with an exon 2 breakpoint." (PMID 39575425, 2024). "Those tumors with HRD were all diagnosed as high grade serous carcinoma, specifically harboring fusions involving NRG1 and the JAG1, SPON1, and TNFRSF12A partner genes." (PMID 39575425, 2024). "Moreover, compared to low grade serous carcinoma, the cancers harboring NRG1 fusions demonstrated statistically lower expression of TNFA signaling genes and those associated with the epithelial-mesenchymal transition." (PMID 39575425, 2024). "There were no significant pathways enriched when comparing NRG1 fusion-positive tumors with fusion-negative high grade serous carcinomas." (PMID 39575425, 2024).
sickle cell disease (1 paper, 2024). Sickle cell anemias are chronic hemolytic diseases that may induce three types of acute accidents: severe anemia, severe bacterial infections, and ischemic vasoocclusive accidents (VOA) caused by sickle-shaped red blood cells obstructing small blood vessels and capillaries. "NRG1 levels are elevated in plasma and brain tissue of transgenic sickle cell disease and ischemic mice and prevent the expression of inflammatory cytokines, chemokines, and adhesion molecules." (PMID 39312480, 2024).
spinal cord injury (1 paper, 2019). Penetrating and non-penetrating injuries to the spinal cord resulting from traumatic external forces (e.g., WOUNDS, GUNSHOT; WHIPLASH INJURIES; etc.). "We recently discovered a novel role for neuregulin‐1 (Nrg1) signaling in mediating spontaneous regenerative processes and functional repair after spinal cord injury (SCI)." (PMID 30637799, 2019).
status epilepticus (1 paper, 2017). Status epilepticus is defined as a continuous seizure lasting more than 30 min, or two or more seizures without full recovery of consciousness between any of them. "Here, we examined the contribution of neuropsin–NRG1 signaling to the pathological functions of ErbB4-expressing, parvalbumin-positive GABAergic interneurons in the kainate (KA)-induced status epilepticus mouse model." (PMID 28267150, 2017).
tauopathy (1 paper, 2023). Neurodegenerative disorders involving deposition of abnormal tau protein isoforms (tau proteins) in neurons and glial cells in the brain. "Immunofluorescent labeling of NRG1 in the CA1 validated downregulation of NRG1 protein in tauopathy and its rescue by deleting Cgas." (PMID 37095396, 2023).
ulcerative colitis (1 paper, 2024). An inflammatory bowel disease involving the mucosal surface of the large intestine and rectum. "These Nrg1+Il1r1+ fibroblasts exhibit differentiation potential and actively contribute to epithelial repair during the early stages of ulcerative colitis recovery." (PMID 38674054, 2024).
uveal melanoma (1 paper, 2020). A melanoma derived from melanocytes of the uveal tract. "Furthermore, NRG1 was shown to drive resistance to MEK inhibitors in metastatic uveal melanoma making it a likely candidate." (PMID 33327495, 2020).
Ventricular arrhythmia (1 paper, 2022). "By downregulating MMP-9 and upregulating Cx43, NRG-1 reduces the dysfunctional electrical conductivity caused by acute MI, thereby improving cardiac electrophysiological parameters and reducing the susceptibility to ventricular arrhythmia." (PMID 36012430, 2022).
viral myocarditis (1 paper, 2019). Myocarditis that is caused by an infection with a viral agent. "Employing a well-established murine model of viral myocarditis, we showed that Nup98, Nrg1, and erbB4 are all upregulated in the myocardium during the acute phase (7 dpi)." (PMID 31396490, 2019).